IRAK1 (interleukin 1 receptor associated kinase 1)
Diseases named in the same sentence as IRAK1 in open-access papers (continued):
Sharing a sentence is not in itself a finding about the gene and the disease.
autoimmune disease (20 papers, 2010 to 2024). A disorder resulting from loss of function or tissue destruction of an organ or multiple organs, arising from humoral or cellular immune responses of the individual to their own tissue constituents. "The well-established fact that X-linked IRAK1 polymorphisms host susceptibility to autoimmune diseases prompts us to investigate the relevance of IRAK1 gene polymorphism with the risk of NMOSD." (PMID 34531808, 2021). "Multiple IRAK1 polymorphisms have also been reported to be associated with the susceptibility of several other autoimmune disorders." (PMID 34531808, 2021). "Several studies have demonstrated that the IRAK1 polymorphism may be related to autoimmune diseases, including SLE, RA, and autoimmune thyroid diseases." (PMID 34531808, 2021). "Interestingly, the IRAK1 gene is located on the Xq28 region that harbours several SNPs that have also been associated with susceptibility to autoimmune diseases." (PMID 28271077, 2017). "Compounds such as pacritinib and JH-X-119-01 exhibit potent effects on hematological malignancies and autoimmune diseases, highlighting the clinical potential of targeting IRAK1." (PMID 38792088, 2024). "Preclinical evidence on the involvement of IRAK1 in autoimmune diseases has emerged over the past years, but many studies had limitations." (PMID 35801586, 2022). "The IRAK1-NF-κB pathway plays a significant part in regulating the inflammatory activity of autoimmune diseases." (PMID 32760274, 2020). "Interleukin-1 receptor associated kinase-1 (IRAK1) exhibits important roles in inflammation, infection, and autoimmune diseases; however, only a few inhibitors have been discovered." (PMID 33014870, 2020). "Polymorphisms in four genes encoding proteins that control the MyD88-IRAK4-IRAK1 pathway have been reported to predispose to SLE and other autoimmune diseases in many human populations, namely, TLR7, IRAK1, TNIP1, and TNFAIP3." (PMID 31694920, 2019). "Furthermore, the effectiveness of IRAK1/4 inhibitors has been demonstrated in autoimmune disease, alcoholic liver injury, and carotid endothelial hyperplasia studies." (PMID 35699749, 2022). "Collectively, these results suggest that IRAK1 may play a vital role in autoimmune diseases, and further study of IRAK1 is warranted." (PMID 34531808, 2021). "Once the IL1-Rs and toll-like receptors (TLRs) are activated, IRAK4 is recruited to form the signaling complex with myeloid differentiation primary-response gene 88 (MyD88) and then IRAK1 is phosphorylated, which plays a crucial role in inflammation, infection, and autoimmune diseases." (PMID 33014870, 2020). "Current literature also confirms contribution of some escapes genes including CD40L, IRAK-1, TLR7, CXORF21 and XIAP to the female bias of autoimmune diseases especially SLE disease." (PMID 33297945, 2020). "Reviewing present literature for the contribution of some escapes genes including CD40L, IRAK-1, TLR7, CXORF21 and XIAP confirms their primary attributions to the female bias of autoimmune diseases especially SLE disease." (PMID 33297945, 2020). "Although it is unclear at present how IKKα links to IRAK1, either kinase appears to be the gateway for activation of IRF7 to induce IFN-α production in pDCs and both could be potential targets for the treatment of autoimmune disorders." (PMID 20470398, 2010).
viral infection (18 papers, 2009 to 2024). "Transcription factors with high binding affinities in IRAK1-DMR were significantly enriched for canonical pathways associated with viral infection and carcinogenic transformation in the Kyoto Encyclopedia of Gene and Genomes analysis." (PMID 36226067, 2022). "Therefore, SLE patients treated with IRAK1 or IRAK4 inhibitors may have less risk for developing severe viral infection compared with patients given anti-IFN therapy." (PMID 27807192, 2016). "Viral infection of the grass carp was demonstrated to recruit Irak1 to the cell membrane possibly indicating that it is recruited to transmembrane TLRs." (PMID 26266270, 2015). "In this stable cell line, NF-κB activity was enhanced by EV71 infection and R848 stimulation, but attenuated in the presence of shTLR7, shMyD88, shIRAK1, shNF-κB p65, and shNF-κB p50, confirming that TLR7, MyD88, and IRAK1 are involved in the activation of NF-κB during viral infection." (PMID 28854257, 2017). "However, during the time-course of viral infection, the total IRAK1 remained unchanged, actin was used as the internal loading control." (PMID 24278275, 2013). "During viral infection, miR-146a-5p suppresses the production of type-I interferon by targeting not only IRAK2, TRAF6, and IRAK1 but also STAT-1 and IRF-5." (PMID 38787176, 2024). "The qRT-PCR results indicated an up-regulation trend for DDX58, STAT1, and MX1, while IRAK1, MAPK11, RELA, and ICAM1 exhibited a down-regulation trend as the duration of the viral infection increased." (PMID 38673764, 2024). "Given the importance of the IRAK1 protein to TLR and IL-1 signaling, the host’s capacity to respond to viral infection would be significantly perturbed if the CP–IRAK1 interaction suppressed the capacity of the IRAK1 protein to function." (PMID 33673546, 2021). "For example, it has been shown that miR-146a is upregulated during viral infection in macrophages and acts as a negative regulator of the retinoic acid-inducible gene I (RIG-I)-like helicases by targeting not only IRAK1 but also TRAF6 and IRAK2." (PMID 23028621, 2012). "The diminishing IRAK1 levels over time during the viral infection suggest a negative feedback mechanism in response to antiviral and antibacterial infections, potentially enhancing the S. aureus infection by modulating downstream inflammatory pathways." (PMID 38673764, 2024). "TRAF6, IRAK1 and IRAK2 play major roles in regulation of immune responses during viral infections." (PMID 25083878, 2014). "In addition, IRAK1 overexpression upregulated IFN-λ1 and -λ3 expression during viral infection." (PMID 36643411, 2022).
diabetes (17 papers, 2015 to 2026). "Of note, a miR-146 deficiency in diabetes correlates with increased inflammation (for insufficient inhibition of IRAK1/TRAF6) and fibrosis (for expression of fibronectin)." (PMID 37685844, 2023). "The analysis of individual studies on miR-146 in the context of diabetes yielded a heatmap that showcased the prevalence of several genes, namely IRAK1, TRAF6, IL-6, TNF-α, NUMB, EGFR, and TGFβ-1, among others." (PMID 37560309, 2023). "By genotyping 4 loci on the IRAK1 gene on the X chromosome of 996 Caucasian patients with Type 2 diabetes (467 men and 529 women), the Diabetes Heart Study identified two major haplotypes, CTTT (82%) and TCCG (13%), in the IRAK1 gene." (PMID 35345264, 2022). "miR-146a-mediated downregulation of IRAK1 is involved in a wide spectrum of diseases, including autoimmune disorders, cancer, diabetes, or neuropathic pain 54-57, as well as in cerebral, hepatic, or intestinal IRI 58-60." (PMID 32863945, 2020). "In an analysis of haplotypes of 996 Caucasian patients in the Diabetes Heart Study, the IRAK1 TCCG haplotype, present in 13%, was significantly (P = 0.0004) associated with greater CRP concentrations in women, but not in men." (PMID 30279971, 2018). "But diabetes causes a significant increase in the expression of TRAF6 and IRAK1 (p<0.05) and NF-kB (p<0.01) genes in the diabetic group compared with the control group." (PMID 27123424, 2016). "In diabetics, IRAK-1 protein expression in the adipose tissue was also significantly higher in obese and overweight individuals as compared with lean subjects as shown by immunohistochemistry." (PMID 26312071, 2015). "Swimming exercise, on the other hand, led to a substantial drop in the expression levels of miR-146a, NF-κB, and inflammatory cytokines and a significant rise in the expression levels of TRAF6 and IRAK1 in the exercise-diabetes group as compared to the diabetic group." (PMID 36911496, 2023). "These authors used a model of diabetes induced using the drug streptozotocin and identified decreased NFkB and MyD88 activity, along with IRAK-1 phosphorylation, leading to a decrease in circulating chemokines and cytokines in TLR2−/−, compared with wild-type, mice." (PMID 28164040, 2017). "This process may contribute to the development of diabetes induced structural and functional changes and is mediated through NF-κB via IRAK1 and TRAF6." (PMID 28301595, 2017). "However, little is known about the role of IRAK-1 in diabetes." (PMID 28824448, 2017). "Saponins also regulate the IRAK1/TRAF6 pathway by increasing the expression of miR‐146a, reducing inflammation, and improving diabetes by inhibiting the NF‐κB pathway." (PMID 41549047, 2026). "The results revealed that IRAK1, TRAF6, NUMB, and STX3 are direct targets of miR-146 in the context of diabetes." (PMID 37560309, 2023). "SRA1 expression associated with TLR2, IRAK1, and IRF3 expression only in individuals with obesity, regardless of diabetes status." (PMID 36552771, 2022). "Diabetes increased TLR4-mediated inflammation, whereas DP inhibited the protein expression of the TLR4 pathway (TLR4, Myd88, IRAK1, and TRAF6) and reduced the mRNA expressions of IL-1β, IL-1α, IL-6, and TNF-α and the protein expressions of TNF-α, IL-1β, and COX-2." (PMID 35463063, 2022).
hepatocellular carcinoma (17 papers, 2016 to 2024). A malignant tumor that arises from hepatocytes. "Our further analysis revealed specific associations between IRAK1 expression profiles and clinicopathological parameters of hepatocellular carcinoma." (PMID 36421353, 2022). "This work was undergone to provide potential diagnostic biomarkers and therapeutic targets for hepatocellular carcinoma, and to afford hit natural compounds as potential IRAK1 inhibitors and suppressors of IRAK1-related pathways to be used in targeted therapy." (PMID 36421353, 2022). "In hepatocellular carcinoma (HCC), IRAK1 upregulation is associated with poor therapy response, metastasis, and an increase in tumor size." (PMID 37370720, 2023). "Herein, we systematically explored the importance of IRAK1 in the diagnosis, prognosis, and targeted therapy of hepatocellular carcinoma." (PMID 36421353, 2022). "IRAK1 is overexpressed in most hematologic malignancies, non–small cell lung carcinoma, and hepatocellular carcinoma." (PMID 36421353, 2022). "In cell culture and xenograft tumor models, gain of IRAK1 promotes tumorigenic growth and metastasis of breast, head neck, and hepatocellular carcinoma." (PMID 36226067, 2022). "Our findings revealed, for the first time, the potential of the hit natural compounds as IRAK1 inhibitors and IRAK1/NF-κB signaling suppressors to be used in targeted therapy for hepatocellular carcinoma." (PMID 36421353, 2022). "This study aimed to explore clinical significance of interleukin-1 receptor-associated kinase 1 (IRAK1) in the diagnosis, prognosis, and targeted therapy of hepatocellular carcinoma." (PMID 36421353, 2022). "In this study, we systematically explored the significance of IRAK1 in the diagnosis, prognosis, and targeted therapy of hepatocellular carcinoma." (PMID 36421353, 2022). "As for hepatocellular carcinoma, the total alteration rate of IRAK1 was rather high, in which mRNA high relative to normal samples predominated." (PMID 36421353, 2022). "Correlations between IRAK1 expression profiles, clinicopathological parameters, and survival profiles of hepatocellular carcinoma were revealed." (PMID 36421353, 2022). "Alterations of IRAK1 occurred in 217 out of 348 hepatocellular carcinoma cases, with a frequency of 62.4%." (PMID 36421353, 2022). "Also, IRAK1 augments cancer stemness and resistance to sorafenib treatment, the effective first-line multi-kinase inhibitor in hepatocellular carcinoma (HCC)." (PMID 37031183, 2023). "Interestingly, IRAK1 overexpression was also observed in hepatocellular carcinoma, augmenting cancer stemness and drug resistance." (PMID 35669566, 2022). "However, there are few studies on the screening of IRAK1 inhibitors from natural compounds for targeted therapy of hepatocellular carcinoma." (PMID 36421353, 2022). "The knockdown of IRAK1 suppresses the growth of hepatocellular carcinoma cells." (PMID 36421353, 2022). "We found that IRAK1 was highly expressed in most cancer types (including hepatocellular carcinoma) and may be a pan-cancer biomarker." (PMID 36421353, 2022). "Moreover, for most of them (18 cancer types, including hepatocellular carcinoma), IRAK1 expression was higher in tumors than in normal tissues (for hepatocellular carcinoma, the significance was p < 0.001)." (PMID 36421353, 2022). "The knockdown of IRAK1 attenuates the growth of hepatocellular carcinoma cells." (PMID 36421353, 2022). "The results indicated a higher expression of IRAK1 in hepatocellular carcinoma tissues." (PMID 36421353, 2022). "In 2020, Chen and colleagues elucidated a mechanism by which IRAK1 promotes metastasis in hepatocellular carcinoma (HCC) through the activation of the NLRP3/MAPKs/IL-1β pathway." (PMID 39451208, 2024).
hepatocellular carcinoma (continued). "The inhibition of IRAK1 by gene silencing and small molecule inhibitors was found to induce apoptosis and a decrease in cell viability in melanoma, gastric cancer, lymphoblastic leukemia, pancreatic cancer, Kaposi carcinoma, cervical cancer, and hepatocellular carcinoma." (PMID 37370720, 2023). "The pharmacological inhibition of IRAK1 by IRAK1/4 inhibitor I was shown to have both antiproliferative and antimetastatic effects on hepatocellular carcinoma (HCC) cells." (PMID 37370720, 2023). "Moreover, as the key node of IRAK1/TRAF6/NF-κB signaling, IRAK1 is rarely investigated in terms of screening of natural compounds for potential inhibitors and signaling suppressors to be used in the targeted therapy of hepatocellular carcinoma." (PMID 36421353, 2022). "Our findings suggest that IRAK1 may play biologically predictive roles in hepatocellular carcinoma." (PMID 36421353, 2022). "In addition, IRAK1 have reported that promotes the progression of hepatocellular carcinoma by participating in the chronic inflammation mediated by macrophages, which is consistent with the positive correlation between IRAK1 and macrophage expression in liver cancer found in this study." (PMID 35669566, 2022). "IRAK1 was reported to be overexpressed and correlated with advanced tumor stages and poor patient prognosis in hepatocellular carcinoma (HCC), lung cancer, and endometrial carcinoma." (PMID 35211171, 2022). "For example, IRAK1 was upregulated in hepatocellular carcinoma (HCC) tissue." (PMID 37108068, 2023). "It was previously shown that IRAK1, in the TLR/IRAK pathway, is significantly upregulated in hepatocellular carcinoma (HCC) and may promote self-renewal, tumorigenicity, and liver tumor-initiating cell marker expression." (PMID 36138026, 2022). "In hepatocellular carcinoma, the alteration rate of IRAK1 was rather high (62.4%), in which mRNA high relative to normal predominated (58.9%)." (PMID 36421353, 2022). "Until now, the specific clinical significance of IRAK1 expression in hepatocellular carcinoma is not fully revealed, especially its correlation with clinicopathological parameters." (PMID 36421353, 2022). "However, the role of IRAK1 in hepatocellular carcinoma (HCC) remains little known." (PMID 27619757, 2016).
rheumatoid arthritis (16 papers, 2008 to 2026). A chronic, systemic autoimmune disorder characterized by inflammation in the synovial membranes and articular surfaces. "A recent study demonstrated that a 3′UTR polymorphisms of IL-1R associated kinase (IRAK1) gene was associated with rheumatoid arthritis (RA) susceptibility." (PMID 21674042, 2011). "rs3027898 (A>C) in the 3′UTR of IRAK1 (interleukin-1 receptor-associated kinase), a target gene of miR-146a, has been shown to be involved in rheumatoid arthritis (RA) pathogenesis." (PMID 25118158, 2014). "Elevated levels of miR-146a was found in synovial fibroblast and blood mononuclear cells of rheumatoid arthritis patients while the levels of IRAK1 and TRAF6 mRNAs were similar to those of controls." (PMID 28319200, 2017).